MAL2 (mal, T cell differentiation protein 2)
Diseases named in the same sentence as MAL2 in open-access papers (continued):
Sharing a sentence is not in itself a finding about the gene and the disease.
cancer (continued). "Additionally, high transcriptional expression of PDCD6, GNG5, PHF6, MAL2, SLC25A15 and PTDSS1 were significantly correlated with BLCA individual cancer stages and molecular subtypes." (PMID 35503998, 2022). "Furthermore, we performed a pan-cancer analysis of predicted target genes (PDCD6, GNG5, PHF6, MAL2, SLC25A15 and PTDSS1) by using TIMER." (PMID 35503998, 2022). "Then, we focused on the data mining of MAL2 methylation, function enrichment, PPI and GGI networks, cancer pathway, and drug sensitivity in OC, indicating that MAL2 may be a potential drug target of OC." (PMID 35111745, 2021). "And TPD52 exhibited frequent overexpression in liver metastasis tissues relative to primary carcinoma tissues (P = 0.042), while MAL2 in lymphnode and liver metastasis tissues showed no significant elevation." (PMID 28562687, 2017). "If MAL2 similarly regulates MUC1 expression and/or distribution in cancer cells, increased MAL2 levels could alter cancer cell biology in several ways." (PMID 19175940, 2009). "However, how MAL2 overexpression regulates tumorigenesis in CRC is still unclear, which might be involving the modulation on cancer-related signal pathways or cell-cell interactions." (PMID 28562687, 2017). "Therefore, we suppose that the detection of CCNE2 and MAL2 transcripts in the blood of cancer patients is indicative for CTC presence (which had not been verified by immunocytochemistry)." (PMID 21129172, 2010). "It is striking to note that MAL2, a chromosome 8q24 amplification target, has now been shown to bind MUC1 and D52, both of which are amplified and/or overexpressed in breast and other cancers strongly suggesting that these proteins have co-operating functions in cancer cells." (PMID 19175940, 2009). "However, there was no systematic research analyzing the role of MAL2 in human cancers." (PMID 35111745, 2021). "However, MAL2 expression in lymph node and liver metastasis tissues showed no significant elevation compared with primary carcinoma in our study, suggesting that MAL2 might not be directly correlated with tumor metastasis through lymph node and liver." (PMID 28562687, 2017). "Focusing only on the highly statistically significant cases (p ≤ 0.001), the correlation with MAL2 expression in BRCA, which occupied the first position in the list of new cancer cases in 2020 with 12.5% of the cases, is of particular note." (PMID 37345137, 2023). "A panel of six genes (CCNE2, DKFZp762E1312, EMP2, MAL2, PPIC and SLC6A8) were over-expressed in cancer cell lines and were absent in healthy women." (PMID 29132396, 2017). "Immunohistochemical analyses showed that MAL2 (P<0.001) and TPD52 (P<0.001) were significantly highly expressed in primary carcinoma tissues compared with adjacent non-cancerous mucosa tissues." (PMID 28562687, 2017). "However, MAL2 (n = 58, P = 0.55) and TPD52 (n = 58, P = 0.672) protein expressions in lymphnode metastasis tissues (data not shown) and MAL2 expression in liver metastasis tissues (n = 38, P = 0.782) did not exhibit significant elevation relative to primary carcinoma groups." (PMID 28562687, 2017).
tumor (32 papers, 2009 to 2026). "MAL2 was overexpressed in tumors and was associated with poor prognosis, and MAL2 knockdown improved major histocompatibility complex type 1 (MHC-1) recognition on tumor surfaces by CD8 + T cells, highlighting the role of MAL2 in immune regulation." (PMID 38769215, 2024). "By interacting with MHC-I and RAB, MAL2 caused the degradation of MHC-I, promoted tumor antigen endocytosis, and suppressed their presentation." (PMID 38769215, 2024). "Although MAL2 is widely expressed in both normal and tumor tissues, it is mainly enriched in most tumor tissues." (PMID 38831979, 2024). "We screened the Z8 small-molecule compound, which targets KK-LC-1 and has excellent tumor cell killing ability by inhibiting MAL2/MUC1-C/PI3K/AKT/mTOR pathway." (PMID 36895039, 2023). "In conclusion, MAL2 plays a potential role in BC metastasis and serves as a tumor promoter in BC cells." (PMID 37480012, 2023). "It has been shown that the suppression of MAL2 has enhanced the cytotoxicity of tumor-infiltrating CD8+ T cells and suppressed breast tumor growth, which suggests that this gene can be a potential biomarker for breast cancer therapy." (PMID 35205681, 2022). "To begin investigating the mechanism by which MAL2 influences cell proliferation and tumor growth, we performed phosphorylated proteomics to measure the changes in protein expression of NCI-H23 with or without MAL2 overexpression." (PMID 35437691, 2022). "MAL2 overexpression has been previously shown to reduce tumor cells’ antigen presentation by promoting the endocytosis of tumor antigens." (PMID 36224576, 2022). "MAL2 overexpression markedly promoted tumor growth as indicated by increased tumor volume and weight." (PMID 35437691, 2022). "We measured the differences in MAL2 expression in tumor and adjacent tissues using the independent-sample Wilcoxon rank sum test and the paired Wilcoxon rank sum test." (PMID 34567213, 2021). "Based on the results of the meta-analysis of six data sets, including 10 analyses using the Oncomine database, the results indicated MAL2 overexpression in tumor tissues (median rank = 476.5, P=6.77E − 13)." (PMID 34567213, 2021). "MAL2 protein is expressed in a variety of epithelial cells, peripheral neurons, mast cells, and dendritic cells and is crucial in immunity, tumor development, and other physiological and pathological processes." (PMID 35111745, 2021). "In all, 18 different HCC cases, 23 CC cases and 20 RCC cases containing both (adjacent) benign and tumor components were labeled with antibodies against MAL2 and Ki-67 (to assess the proliferative index)." (PMID 32059473, 2020). "Mutational analysis revealed that a putative Ena/VASP homology 1 recognition site confers the MAL2-phenotype suggesting its role in tumor suppression involves actin remodeling." (PMID 32059473, 2020). "The decreased MAL2 labeling was apparent in the tumor component (T) of a patient liver biopsy when examined by eye." (PMID 32059473, 2020). "Blinded and independent analysis of human HCC, CC and RCC tissue revealed that MAL2 protein expression levels were surprisingly, significantly decreased in malignant lesions more consistent with MAL2 function as a tumor suppressor." (PMID 32059473, 2020). "Correlation analyses by Pearson’s chi-square test demonstrated that MAL2 in tumors was positively correlated with tumor status (pathological assessment of regional lymph nodes (pN, P = 0.024)), and clinic stage (P = 0.017)." (PMID 28562687, 2017). "MAL2 was shown to be positively correlated with tumor status (pathological assessment of regional lymph nodes (pN, P = 0.024)) and clinic stage (P = 0.017)." (PMID 28562687, 2017). "Studies have shown that TNBC patients with high MAL2 expression have a poorer prognosis, with a significantly lower 5-year survival rate (71.33% vs 89.59%, p = 0.0224), independent of PD-1 expression levels and clinical pathological features of the tumor." (PMID 40666073, 2025).
tumor (continued). "Since both MAL2 and PD-L1 modulate tumor immune response, confirming their interactions may uncover the role of MAL2 as a novel prognostic marker and therapeutic target in TNBC." (PMID 38769215, 2024). "The MAL2 protein may also play a role in immune evasion by reducing antigen presentation on tumor cells." (PMID 39188717, 2024). "In terms of tumor stage, MAL2 was highly expressed in T4 (p = 0.021)." (PMID 40625454, 2024). "MAL-family proteins overexpressed in tumor cells —for example, MAL2 in BRCA, PAAD, and UCEC, and MALL in PAAD—could serve as putative target antigens for CAR-T cell therapy." (PMID 37345137, 2023). "Using these tumor samples, we also detected the expression of KK-LC-1, MAL2 and MUC1." (PMID 36895039, 2023). "Since our results demonstrate that NSMCE2 and MAL2 gene expression levels are reduced by pharmacological SE blockade, targeting SEs could work as a therapeutic approach to reduce these tumor promoting processes." (PMID 36224576, 2022). "Finally, among the genes co-expressed with CMTMs, studies have reported that MAL2, which was positively correlated with the expression of CMTMs, can act as an oncogene to inhibit tumor antigens and promote tumor immune escape." (PMID 36110202, 2022). "However, genes associated with tumor metastasis and tumor cell proliferation (SPP1, GSTA1, MAL2, and MGST1) were found to be highly expressed in LUSC1, LUSC2, LUSC4 samples." (PMID 35899203, 2022). "In xenograft mice, knockout of MAL2 dramatically alleviated tumor growth." (PMID 35111745, 2021). "Together these data are consistent with MAL2 function as a tumor suppressor." (PMID 32059473, 2020). "To determine whether endogenous MAL2 expression correlates with tumor suppression, we continued our analysis in human HCC-derived Hep3B cells." (PMID 32059473, 2020). "MAL2 and TPD52 staining in tumor cells and associations with clinicopathologic characteristics." (PMID 28562687, 2017). "In addition, the tumor marker CEA was also shown to be positively associated with MAL2 positive expression (P = 0.005), suggesting that MAL2 expression in tumor cells was a potential predictive factor for CRC." (PMID 28562687, 2017). "Moreover, RT-qPCR showed the identical results to immunohistochemical analyses, indicating that RNA expression of MAL2 or gene copy number in tumor tissues was increased." (PMID 28562687, 2017). "Additionally, MAL2 in tumors was demonstrated to be positively correlated with tumor status (pathological assessment of the regional lymph nodes), and clinic stage." (PMID 28562687, 2017). "Furthermore, the overexpression of MAL2 partially reversed the anti-tumor effects of APS." (PMID 41605797, 2026). "Since we also demonstrated that downregulation of NSMCE2 and MAL2 gene expression can be achieved by blocking SEs, collectively these data suggest that both mechanisms (i.e., SE-driven dysregulation and gene amplification) can increase expression of these oncogenes in tumor cells." (PMID 36224576, 2022). "Based on these results, one possible explanation to reconcile MAL2’s function as a tumor suppressor with its upregulated expression and link to bad prognosis is that overexpressed MAL2 harbors mutations in the FPAP motif thereby abolishing its tumor suppressor activities." (PMID 32059473, 2020). "Similarly, comparable overall survival was noted for tumours with high visually-scored MAL2 levels relative to all others, whereas significantly improved overall survival was noted in patients with tumours with high TPD52 staining (log-rank test, p < 0.001, n = 124)." (PMID 20846453, 2010). "Eight genes exhibited greater than 340-fold increases in expression in tumor tissues (CLDN6, KLK7, WNT10A, MYBL2, MAL2, KRT7, PRSS8, EPCAM; Median (Range) of fold increase = 344 (261–7267))." (PMID 41465326, 2025).
tumor (continued). "Another gene found in the CNA dataset is MAL2, a gene identified to determine the turnover of the antigen-loaded MHC–I complex and reduces antigen presentation on a tumor cell, which promotes immune evasion." (PMID 35205681, 2022). "Knockout of MAL2 in patient-derived tumour organoid models resulted in enhanced CD8+ T cell-mediated cytotoxicity, thus making MAL2 a potential therapeutic target." (PMID 35343573, 2022). "In this study, we explored the expressions of MAL2 and TPD52 in tumor specimens resected from 123 CRC patients and the prognostic values of the two proteins in CRC." (PMID 28562687, 2017). "Although the results from the TCGA database analysis align with the results from our TMA cohort, MAL2 expression seems independent of PD-L1 status, tumor grade, stage, size, lymph node invasion, and metastasis." (PMID 38769215, 2024). "MAL2 expression did not correlate with stage, grade, tumor size, lymph node invasion, metastasis, and PD-1 expression." (PMID 38769215, 2024). "Furthermore, MAL2 downregulation reversed EMT, reduced downstream β-catenin and c-Myc expression in vitro, and inhibited tumor metastatic capacity in vivo." (PMID 37480012, 2023). "Overexpression of MAL2 resulted in the hyper-activation of the MAPK/mTOR signaling pathway in NSCLC cells, leading to active ribosome biogenesis which promoted cell proliferation and tumor growth." (PMID 35437691, 2022). "Together these data indicate that the FPAP (but not VPPPP) motif mediates MAL2 tumor suppressor activity." (PMID 32059473, 2020). "Furthermore, we determined that the expression of MAL2 and TPD52 in tumor cells was an independent predictor of OS according to the multivariate Cox model analysis." (PMID 28562687, 2017). "We found no direct correlation between the expression of PD-L1 and MAL2, but both proteins partake in tumor immunoregulation and may be intertwined in mediating tumor immune escape." (PMID 38769215, 2024). "MAL2 did not correlate with stage, grade, tumor size, and lymph node invasion." (PMID 38769215, 2024). "An IHC study indicated that MAL2 protein expression is downregulated in LIHC and CHOL compared with the expression in benign adjacent tissue, even though chromosome 8q24 amplification suggested that MAL2 could be overexpressed in these two types of tumor." (PMID 37345137, 2023). "However, MAL2 labeling in the tumor lesions was decreased and no dense immunoreactive clusters were observed." (PMID 32059473, 2020).
infection (2 papers, 2020 to 2022). The state of being infected such as from the introduction of a foreign agent such as serum, vaccine, antigenic substance or organism. "As observed for WIF-B cells, MAL2 in Hep3B cells is relatively long-lived, and even after 4 days post-infection with anti-sense MAL2 adenoviruses, only partial knockdown (~30% reduction) was achieved." (PMID 32059473, 2020).
MAL2 also shares sentences with these, for which no sentence is quoted: renal cell carcinoma (3 papers); chronic pancreatitis (2); gastric adenocarcinoma (2); lung squamous cell carcinoma (2); melanoma (2); thymoma (2); uterine corpus endometrial carcinoma (2); Adc (1); adenocarcinoma (1); benign tumors (1); bladder (1); bladder tumor (1); bladder urothelial carcinoma (1); cervical squamous cell carcinoma (1); clear cell carcinomas (1); connective tissue disorder (1); endometrioid ovarian carcinomas (1); Fibroadenoma (1); gastric cancer (1); glioblastoma (1); head and neck squamous cell carcinoma (1); intrahepatic cholangiocarcinoma (1); invasive breast carcinoma (1); liver disease (1); pancreatitis (1); rectal adenocarcinoma (1); rectal cancer (1); renal carcinoma (1); rheumatoid arthritis (1); serous ovarian carcinoma (1).
A further 2 diseases each share a sentence with MAL2 in 1 paper.